SYCP2L (synaptonemal complex protein 2 like)
Description:
Oocyte-specific protein that localizes to centromeres at the dictyate stage and regulates the survival of primordial oocytes.
Synonyms: C6orf177; NO145; dJ62D2.1; POF24
Tractability: No criterion of Open Targets' tractability assessment is met for any kind of drug.
Gene: Protein-coding gene on chromosome 6 (10,886,831 to 10,979,320, forward strand). Ensembl gene ENSG00000153157.
Subcellular location: Nucleus; Chromosome, centromere
Subcellular location (Human Protein Atlas): Nucleoplasm
Gene Ontology:
Cellular component: condensed chromosome, centromeric region; nucleoplasm; nucleus; lateral element; chromosome, centromeric region
Genetic constraint (gnomAD): Loss-of-function variants: 81 observed, 103.67 expected, observed/expected ratio (o/e) 0.78, 90% interval 0.65 to 0.94. The upper end of that interval is the gene's LOEUF score, 0.94, which puts it in group 3 of 6, group 1 being the genes least tolerant of losing a copy. Missense variants: 747 observed, 858.83 expected, observed/expected ratio (o/e) 0.87, 90% interval 0.82 to 0.92. Synonymous variants: 276 observed, 304.15 expected, observed/expected ratio (o/e) 0.91, 90% interval 0.82 to 1.
Homologues: Orthologues: chimpanzee SYCP2L (99% identical), macaque SYCP2L (87% identical), pig SYCP2L (65% identical), dog SYCP2L (55% identical), rat Sycp2l (54% identical), mouse Sycp2l (53% identical), tropical clawed frog sycp2l (35% identical). Paralogues in human: SYCP2 (29% identical).
Diseases named in the same sentence as SYCP2L in open-access papers:
SYCP2L is named in the same sentence as 7 diseases in open-access papers, as found by Europe PMC text mining. Sharing a sentence is not in itself a finding about the gene and the disease. The quoted sentences say what the papers report.
age-related hearing impairment (1 paper, 2024). "Four SNPs mapped to SYCP2L, VAV, SEPSECS, and TMPRSS15 are known to be associated with age-related hearing impairment, multiple sclerosis, pontocerebellar hypoplasia type 2, enterokinase deficiency, respectively." (PMID 38291454, 2024).
breast carcinoma (1 paper, 2025). "Given that SYCP2 has been reported as aberrantly expressed in ovarian and breast cancers—where its overexpression is associated with resistance to therapies targeting the DNA damage response —it is plausible that SYCP2L may exhibit similar aberrant activation in the context of ASCC." (PMID 40559621, 2025).
female infertility (1 paper, 2025). Diminished or absent ability of a female to achieve conception. "While only limited studies have linked SYCP2L to female infertility, its sequence homology with SYCP2 raises the possibility of shared non-canonical functions, such as involvement in the negative regulation of cell death via DNA repair." (PMID 40559621, 2025).
SYCP2L also shares sentences with these, for which no sentence is quoted: enterokinase deficiency (1 paper); multiple sclerosis (1); pontocerebellar hypoplasia type 2 (1); prostate carcinoma (1).